GPATCH2L (G-patch domain containing 2 like)
Synonyms: C14orf118; FLJ20689; FLJ10033
Tractability: PROTAC: UniProt records ubiquitination sites on it; ubiquitination databases record sites on it.
Gene: Protein-coding gene on chromosome 14 (76,151,916 to 76,254,342, forward strand). Ensembl gene ENSG00000089916.
Subcellular location (Human Protein Atlas): Nucleoplasm; Cytosol
Gene Ontology:
Molecular function: protein binding
Cellular component: nucleus
Genetic constraint (gnomAD): Loss-of-function variants: 17 observed, 33.22 expected, observed/expected ratio (o/e) 0.51, 90% interval 0.35 to 0.77. The upper end of that interval is the gene's LOEUF score, 0.77, which puts it in group 3 of 6, group 1 being the genes least tolerant of losing a copy. Missense variants: 306 observed, 411.15 expected, observed/expected ratio (o/e) 0.74, 90% interval 0.68 to 0.82. Synonymous variants: 135 observed, 148.83 expected, observed/expected ratio (o/e) 0.91, 90% interval 0.79 to 1.05.
Homologues: Orthologues: chimpanzee GPATCH2L (100% identical), macaque GPATCH2L (99% identical), pig GPATCH2L (96% identical), dog GPATCH2L (94% identical), guinea pig GPATCH2L (90% identical), rabbit GPATCH2L (89% identical), rat Gpatch2l (85% identical), mouse Gpatch2l (85% identical). Paralogues in human: GPATCH2 (34% identical).
Diseases named in the same sentence as GPATCH2L in open-access papers:
GPATCH2L is named in the same sentence as 2 diseases in open-access papers, as found by Europe PMC text mining. Sharing a sentence is not in itself a finding about the gene and the disease. The quoted sentences say what the papers report.
cancer (2 papers, 2017 to 2022). A tumor composed of atypical neoplastic, often pleomorphic cells that invade other tissues. "GPATCH2, a paralog of GPATCH2L, is upregulated in cancer cells, localizes to the nucleus where it interacts with RNA-processing machinery, and manipulation in culture alters cell proliferation." (PMID 28137300, 2017).
GPATCH2L also shares sentences with these, for which no sentence is quoted: tumor (1 paper).